CLDN14 (claudin 14)
Diseases named in the same sentence as CLDN14 in open-access papers (continued):
Sharing a sentence is not in itself a finding about the gene and the disease.
Calcium nephrolithiasis (3 papers, 2014 to 2022). The presence of calcium-containing calculi (stones) in the kidneys. "Since polymorphisms of WDR72, DGKH, and CLDN14 are predicted to influence in CaSR signaling, our results emphasized the role of abnormal calcium homeostasis in calcium nephrolithiasis." (PMID 35910217, 2022). "Our results indicated that rs578595 at WDR72, rs1037271 at DGKH, rs12654812 at SLC34A1, rs12539707 at HIBADH, and rs12626330 at CLDN14 were associated with the risk of calcium nephrolithiasis in Chinese Han population." (PMID 35910217, 2022). "Our studies suggest that CaSR and CLDN14 are candidate genes to explain the individual predisposition to calcium kidney stones." (PMID 26107257, 2015). "Although further investigation is required, we assumed that the polymorphism of WDR72, DGKH, and CLDN14 could increase the risk of calcium nephrolithiasis by influencing the CaSR signaling." (PMID 35910217, 2022). "Moreover, rs12654812 at SLC34A1 (p = 0.0427, OR = 1.170), rs12539707 at HIBADH (p = 0.0179, OR = 0.734), rs1037271 at DGKH (p = 0.0096, OR = 0.828) and rs12626330 at CLDN14 (p = 0.0080, OR = 1.213) indicated suggestive associations with calcium nephrolithiasis." (PMID 35910217, 2022). "Genetic polymorphisms of CLDN14, CASR, OPN, ORAI1, and VDR were reported to be involved in calcium nephrolithiasis in humans." (PMID 24800221, 2014).
hepatocellular carcinoma (3 papers, 2022 to 2026). A malignant tumor that arises from hepatocytes. "However, low expression of CLDN14 was found in 129/212 (60.8%) patients with primary hepatocellular carcinoma (HCC)." (PMID 35053454, 2022). "In hepatocellular carcinoma (HCC), METTL6 depletion inhibits cell growth, colony formation, migration, invasion, and cell adhesion and reduces the expression levels of cell adhesion proteins such as ITGA1, SPON1, and CLDN14." (PMID 41501031, 2026).
urolithiasis (3 papers, 2019 to 2023). Stone(s) within the urinary tract. "Association between SNP rs219780 of the CLDN14 gene and urolithiasis was characterized by borderline p-value (OR = 2.03; p = 0.05)." (PMID 34054913, 2021). "Genome-wide association studies have revealed a possible association of the genes claudin 14 (CLDN14) and diacylglycerol kinase (DGKH) with urolithiasis in Caucasians (from Iceland and The Netherlands) and Japanese people, respectively." (PMID 30742686, 2019).
colon adenocarcinoma (2 papers, 2023 to 2024). "Multiple groups used TCGA data on colon adenocarcinomas (n = 287) and found that at the RNA level, CLDN14 was upregulated compared to the normal colon." (PMID 38540693, 2024).
colon cancer (1 paper, 2023). "Then, we found that the expression of three deregulated claudins (CLDN11, CLDN14, and CLDN23) is significantly correlated with the shorter survival time of colon cancer patients as well as in the metadata of GSEA datasets." (PMID 37799140, 2023). "Our analysis revealed that the higher expression group of CLDN14 and CLDN11 are significantly correlated with the survival prognosis of colon cancer patients and the low expression group of CLDN23 is significantly correlated with shorter survival time of colon cancer patients." (PMID 37799140, 2023).
diabetes (1 paper, 2024). "Here, we report that during diabetes the expression of cell junction protein, claudin 14 is compromised in the human urine exfoliated cells and in the urinary bladder of type 2 diabetic mouse." (PMID 39162877, 2024).
Down syndrome (1 paper, 2015). "One of them was in the CLDN14 gene in the Down's syndrome breakpoint region, and the second CpG site was located in a non-coding RNA gene on 21q22.3." (PMID 25729447, 2015).
E. coli infection (1 paper, 2020). "We here report the importance of sufficient vitamin D levels to ensure enough high levels of the barrier proteins occludin and claudin-14 in the urinary bladder of postmenopausal women and in mice during E. coli infection." (PMID 31930458, 2020). "However, during E. coli infection, vitamin D induced occludin and claudin-14 in mature superficial umbrella cells of the urinary bladder, as demonstrated by immunohistochemistry." (PMID 31930458, 2020).
glioma (1 paper, 2025). A benign or malignant brain and spinal cord tumor that arises from glial cells (astrocytes, oligodendrocytes, ependymal cells). "Pathway enrichment analysis demonstrated that specific CLDN genes, such as CLDN14 and CLDN11, regulated key pathways, including apoptosis, cell cycle, and DNA damage repair, suggesting their potential roles in glioma progression." (PMID 41425851, 2025).
Hypercalcemia (1 paper, 2023). An abnormally increased calcium concentration in the blood. "Very low levels of Cldn14 were observed in all analysed tissues (data not shown), consistent with the low expression of this negative regulator of paracellular Ca2+ permeability in the absence of hypercalcemia." (PMID 36274099, 2023).
Hypertension (1 paper, 2021). The presence of chronic increased pressure in the systemic arterial system. "One study looked at the different SNPs in the 3′ region of the claudin-14 gene and found the strongest association between the CLDN14 SNP rs219755 (G/A) and 24 h-urinary calcium excretion with higher excretion for the GG genotype compared with GA or AA in patients with hypertension." (PMID 34444650, 2021).
Intellectual disability (1 paper, 2019). "Including this report, there have been no cases with intellectual disability indicating central involvement; therefore, it is possible that the spiral ganglion may be involved in claudin-14 associated HL." (PMID 31527509, 2019).
intestinal infections (1 paper, 2016). "In addition to the known effects of EcN on expression of the sealing TJ proteins ZO-1 and claudin-14, downregulation of claudin-2 can contribute to the efficacy of this probiotic in the treatment of intestinal infections and inflammatory diseases." (PMID 28018313, 2016).
Lewis Lung Carcinoma (1 paper, 2013). "WT, Cldn14-het and Cldn14-null mice were injected subcutaneously with 0.5×106 B16F10 melanoma or Lewis Lung Carcinoma (LLC) cells." (PMID 23675413, 2013).
melanoma (1 paper, 2013). A malignant, usually aggressive tumor composed of atypical, neoplastic melanocytes. "Wild-type (WT), Cldn14 heterozygous (Cldn14-het) and Cldn14-null mice were injected subcutaneously with 0.5×106 B16F10 melanoma cells." (PMID 23675413, 2013).
nephrocalcinosis (1 paper, 2015). Nephrocalcinosis is a disorder that occurs when too much calcium is deposited in the kidneys. "CLDN14 expression would be increased by the activating mutation of CaSR gene and causing nephrocalcinosis." (PMID 26107257, 2015).
preeclampsia (1 paper, 2025). Preeclampsia is a hypertensive disorder of pregnancy that is characterized by new-onset hypertension with proteinuria presenting after 20 weeks of gestation, and depending on mild or severe forms may initially present with severe headache, visual disturbances, and hyperreflexia. "Notably, the F11R, NOTCH1, GRHL3, and CLDN14 genes were associated with preeclampsia-associated PTB." (PMID 40625359, 2025).
tumor (7 papers, 2013 to 2025). "Results showed that the proportion of blood vessels with α-SMA-positive pericyte association was reduced significantly in tumours grown in Cldn14-het mice." (PMID 23675413, 2013). "How does this relate to the loss of lumen formation in a significant proportion of Cldn14-het tumour blood vessels?" (PMID 23675413, 2013). "In addition, the increased tumour vascular fragility that we have observed in Cldn14-het mice is associated with enhanced endothelial proliferation in vivo, ex vivo and in endothelial cell cultures in vitro." (PMID 23675413, 2013). "This disruption of the basement membrane organisation may be the cause of the decreased supporting cell coverage in Cldn14-het tumour blood vessels." (PMID 23675413, 2013). "Considering the possible destabilisation of tumour blood vessels in Cldn14-het animals, we sought to investigate whether loss of Cldn14 affected the leakage of tumour blood vessels." (PMID 23675413, 2013). "Given that extracellular matrix deposition and maintenance are crucial steps in the maturation of tumour blood vessels, we next asked if the distribution of laminin within the blood vessel basement membrane was affected by changes in stromal Cldn14 levels." (PMID 23675413, 2013). "In contrast, hypoxic levels were found to be significantly lower in both B16F10 and LLC tumours grown in Cldn14-het mice when compared with controls." (PMID 23675413, 2013). "In contrast, a high frequency of disorganised laminin deposition around blood vessels, with a ‘shorelining’ pattern, was observed in sections from tumours grown in Cldn14-het mice." (PMID 23675413, 2013). "In contrast, and surprisingly, a discontinuous staining pattern of ZO-1 was observed in the majority of Cldn14-het tumour blood vessels." (PMID 23675413, 2013). "Tail vein injections of pimonidazole HypoxyprobeTM (HPI, Inc.)into tumour-bearing WT, Cldn14-het and Cldn14-null mice showed that the relative levels of tumour hypoxia were similar between WT and Cldn14-null mice." (PMID 23675413, 2013). "Surprisingly, blood vessel densities across midline tumour sections were found to be elevated in tumours grown in Cldn14-het mice when compared with WT and Cldn14-nulls." (PMID 23675413, 2013). "Based on a previous study indicating a role of claudin-14 in tumor angiogenesis, a functional role in endothelial cells might be possible." (PMID 40624709, 2025). "Among them, CLDN14 could promote tumor proliferation, and invasion through the PI3K/AKT/mTOR pathway." (PMID 36098705, 2022). "The changes observed in tumour blood vessel leakage and hypoxia may have been indicative of changes in tumour growth in Cldn14-het mice." (PMID 23675413, 2013). "Given that Cldn14 is a tight junction protein, we first asked whether deletion of Cldn14 could affect tumour endothelial cell-cell junction organisation." (PMID 23675413, 2013). "Analysis of endomucin-stained tumour sections showed that the percentage of closed vessels was elevated in Cldn14-het tumour sections, while lumenated vessel density was unchanged between tumours grown in WT, Cldn14-het or Cldn14-null mice." (PMID 23675413, 2013). "These combined results demonstrate a role for the tight junction protein Cldn14 in maintenance of tumour blood vessel integrity and angiogenesis that was previously unknown." (PMID 23675413, 2013). "In short our data establish that Cldn14 heterozygosity, but not complete deficiency, can affect tumour blood vessel functionality and describe a gene dosage effect of this molecule on angiogenic processes." (PMID 23675413, 2013). "Thus the lack of differences in lumenated blood vessels between genotypes correlates with the similar tumour growth rates in WT, Cldn14-het and Cldn14-null mice." (PMID 23675413, 2013).
tumor (continued). "Taken together, the enhanced total tumour blood vessel density counts in vivo and increased microvessel sprouting ex vivo in Cldn14-hets indicate that partial, but not complete, loss of Cldn14 is sufficient to enhance angiogenic responses, but with compromised functionality." (PMID 23675413, 2013). "Here we have shown that Cldn14 heterozygosity, but not total deficiency, induces destabilisation of tumour blood vessels, which correlates with enhanced vessel leakage and decreased tumour hypoxia without affecting tumour growth." (PMID 23675413, 2013). "However, the precise functions of Cldn14 in angiogenesis in vivo and particularly in tumour angiogenesis are unknown." (PMID 23675413, 2013). "Previous studies exploring the effects of CLDN1, CLDN2, CLDN4, CLDN11, CLDN12, CLDN14, and CLDN23 expression on CRC tumor growth have yielded findings consistent with our results in the present study." (PMID 35281827, 2022). "The consequences of changes in Cldn14 expression levels on tumour blood vessel fragility and angiogenesis have not been addressed previously." (PMID 23675413, 2013). "Since tumour blood vessels appeared disrupted in Cldn14-het mice, but tumour size was not affected, we then examined the numbers of blood vessels in midline sections of size-matched tumours grown in WT, Cldn14-Het and Cldn-14 null mice." (PMID 23675413, 2013). "ZO-1 staining was confined to a continuous pattern of expression at endothelial cell-cell junctions in tumours from both WT and Cldn14-null animals, indicating that Cldn14-deletion was not sufficient to affect the organisation of ZO-1 at cell-cell junctions." (PMID 23675413, 2013). "The apparent lack of correlation between tumour size and blood vessel density suggested that the functionality of the vessels in tumours grown in Cldn14-het mice might have been affected." (PMID 23675413, 2013). "Tumour sections were double immunostained for PECAM and laminin and observations showed that the pattern of laminin deposition was proximate to the blood vessel wall in sections from WT and Cldn14-null mice, indicating, again that Cldn14 deficiency was not sufficient to affect this process." (PMID 23675413, 2013).
cancer (4 papers, 2013 to 2025). A tumor composed of atypical neoplastic, often pleomorphic cells that invade other tissues. "The epigenetic silencing of CLDN14 is significantly correlated with advanced cancer stage and cancer invasiveness." (PMID 40687428, 2025). "Some studies have also described the role of somatic variation of CLDN14 in cancer." (PMID 35291565, 2022). "Cells were positive for claudin-14 in 24.0% (12/50) of tissues adjacent to the cancer." (PMID 24325792, 2013).
infection (3 papers, 2019 to 2022). The state of being infected such as from the introduction of a foreign agent such as serum, vaccine, antigenic substance or organism. "However, during infection, only claudin-14 increased on both the mRNA and protein level, while occludin protein expression remained unchanged." (PMID 35821354, 2022). "Infection with E. coli CFT073 led to an increased expression of both occludin and claudin-14 predominantly in the upper layers of mature umbrella cells close to lumen, suggesting a local vitamin D response that further diminished towards the basal layers of lamina propria or submucosa." (PMID 31930458, 2020). "Exposure to OMVs or COF-SN from either EcN (white bars) or ECOR63 (grey bars) during infection counteracted the EPEC-induced downregulation of occludin and claudin-14, whose expression levels remained close to those of non-infected control cells." (PMID 31315566, 2019).
CLDN14 also shares sentences with these, for which no sentence is quoted: Hypomagnesemia (3 papers); prostate carcinoma (2); sensorineural hearing loss (2); Alport syndrome (1); autosomal recessive deafness (1); calcium oxalate kidney stone (1); lung carcinoma (1); metastasis (1); non-small cell lung carcinoma (1); nonsyndromic deafness (1); ovarian carcinoma (1); Primary Biliary Cirrhosis (1); renal disease (1); sarcoma (1); trisomy 21 (1).